WNT7B (Wnt family member 7B)
Description:
Ligand for members of the frizzled family of seven transmembrane receptors that functions in the canonical Wnt/beta-catenin signaling pathway. Required for normal fusion of the chorion and the allantois during placenta development (By similarity). Required for central nervous system (CNS) angiogenesis and blood-brain barrier regulation.
Tractability: Antibody: UniProt places it where antibodies can reach, with high confidence; its Gene Ontology location is reachable by antibodies, with high confidence; UniProt predicts a signal peptide or a membrane-spanning region. PROTAC: its protein half-life has been measured.
Gene: Protein-coding gene on chromosome 22 (45,920,366 to 45,977,162, reverse strand). Ensembl gene ENSG00000188064.
Subcellular location: Secreted, extracellular space, extracellular matrix; Secreted
Pathways (Reactome):
Signal Transduction: Class B/2 (Secretin family receptors); WNT ligand biogenesis and trafficking
Gene Ontology:
Molecular function: protein binding; receptor ligand activity; cytokine activity; frizzled binding; signaling receptor binding
Biological process: canonical Wnt signaling pathway; cellular response to retinoic acid; fibroblast proliferation; forebrain regionalization; mammary gland epithelium development; neuron differentiation; stem cell proliferation; cell fate commitment; central nervous system vasculogenesis; chemoattraction of dopaminergic neuron axon; chorio-allantoic fusion; developmental growth involved in morphogenesis; embryonic organ development; embryonic placenta morphogenesis; establishment or maintenance of polarity of embryonic epithelium; homeostatic process; in utero embryonic development; inner medullary collecting duct development; intracellular oxygen homeostasis; lens fiber cell development; lobar bronchus development; lung development; lung epithelium development; lung morphogenesis; metanephric collecting duct development; and 20 more
Cellular component: extracellular region; endocytic vesicle membrane; endoplasmic reticulum lumen; extracellular exosome; Golgi lumen; plasma membrane
Genetic constraint (gnomAD): Loss-of-function variants: 19 observed, 36.64 expected, observed/expected ratio (o/e) 0.52, 90% interval 0.36 to 0.76. The upper end of that interval is the gene's LOEUF score, 0.76, which puts it in group 3 of 6, group 1 being the genes least tolerant of losing a copy. Missense variants: 423 observed, 512.39 expected, observed/expected ratio (o/e) 0.83, 90% interval 0.76 to 0.89. Synonymous variants: 243 observed, 215.15 expected, observed/expected ratio (o/e) 1.13, 90% interval 1.02 to 1.26.
Homologues: Orthologues: pig WNT7B (99% identical), chimpanzee WNT7B (94% identical), macaque WNT7B (94% identical), rat Wnt7b (93% identical), dog WNT7B (93% identical), guinea pig WNT7B (93% identical), tropical clawed frog wnt7b (91% identical), zebrafish wnt7bb (86% identical), mouse Wnt7b (75% identical), Drosophila melanogaster Wnt2 (48% identical), Caenorhabditis elegans cwn-2 (44% identical), Drosophila melanogaster Wnt5 (38% identical), and 3 more. Paralogues in human: WNT7A (77% identical), WNT2B (48% identical), WNT4 (47% identical), WNT16 (45% identical), WNT2 (44% identical), WNT5A (44% identical), WNT5B (44% identical), WNT3 (44% identical), WNT3A (42% identical), WNT10A (42% identical), WNT6 (40% identical), WNT10B (39% identical), and 6 more.
Diseases named in the same sentence as WNT7B in open-access papers:
WNT7B is named in the same sentence as 102 diseases in open-access papers, as found by Europe PMC text mining. Sharing a sentence is not in itself a finding about the gene and the disease. The quoted sentences say what the papers report.
breast carcinoma (31 papers, 2015 to 2025). "Others reported that the development of human breast cancer is strongly associated with overexpression of the Wnt family ligand Wnt7B in the tumor stroma and that isolated human breast carcinoma TAMs express Wnt7B." (PMID 36670988, 2023). "In line with this, we observed enhanced levels of WNT7B in breast cancer cells with loss-of-function mutations in MAP2K4 and MAP3K1." (PMID 31766464, 2019). "WNT7B expression was significantly associated with poor prognosis in breast cancer." (PMID 37584250, 2023). "A high expression of Wnt7b was associated with poor breast cancer prognosis." (PMID 34457116, 2021). "To illustrate this approach, we will build a case study around Wnt7b, a gene that has been implicated in mammary gland development and breast cancer, but whose precise activity and mode of regulation remain unknown." (PMID 33625717, 2020). "Finally, analysis of 166 estrogen receptor (ER) positive human breast cancer cases showed enhanced levels of WNT7B in breast cancers with loss-of-function mutations in the upstream JNK pathway components MAP2K4 and MAP3K1." (PMID 31766464, 2019). "Clinicopathological analysis revealed marked upregulation of WNT2 and WNT7B in HER2-positive breast cancer, suggesting a potential synergy between WNT signaling and HER2-driven oncogenic pathways." (PMID 41044153, 2025). "The involvement of Wnt ligands in TGF-β–induced invasiveness has been previously reported for breast cancer cells, where Wnt7a and Wnt7b were found to be induced by the Smad3–JunB cooperative transcriptional activation." (PMID 38141763, 2024). "Research shows that WNT7B in breast cancer can stimulate endothelial cells to produce VEGF for angiogenesis." (PMID 35847885, 2022). "MiR-640 was previously noted to be a suppressor in breast cancer, attributed to its inhibitory effects on Wnt7b/β-catenin oncogenic pathway." (PMID 36340580, 2022). "The WNT/β-catenin pathway plays a critical role in tumorigenesis, and Wnt7b was reported to function in mediating metastasis in breast cancer." (PMID 36579891, 2022). "WNT7B is expressed in human breast tissue and its expression has been reported to be altered in breast cancer." (PMID 33625717, 2020). "In breast cancer, WNT7B has not only been shown to be expressed by the tumor cells, but also by myeloid cells present in the local microenvironment." (PMID 33625717, 2020). "Moreover, the oncogenic role of WNT7B, the Wnt family member 7B, has been reported in breast cancer previously, with a major focus on its promotion of invasive behaviors such as angiogenesis and metastasis." (PMID 37033959, 2023). "Furthermore, in mice, Wnt7b was shown to play a crucial role in the malignant progression of luminal breast cancer by promoting angiogenesis, tumor growth, progression, invasion and metastasis." (PMID 36670988, 2023). "In breast cancer cells, WNT7B stimulates cell proliferation and migration." (PMID 36497264, 2022). "Furthermore, transgenic mice overexpressing β-hCG have been shown to develop multiple neoplasms, including breast cancer, also showing that hCG can up-regulate Wnt7b and Wnt5b, thus contributing to pregnancy-induced breast cancer in humans." (PMID 33572731, 2021). "Furthermore, Wnt7B knockdown weakened the mammosphere formation capacity of both types of breast cancer cells." (PMID 33311446, 2020). "Tumor growth in this MMTV-PymT-driven mouse breast cancer was dependent on the WNT7B expression by myeloid cells since in the CSF-1R promoter dependent conditional knock-out model the myeloid selective ablation of Wnt7b reduced tumor growth beyond the failure of the angiogenic switch." (PMID 28197019, 2017). "Myeloid WNT7b mediates the angiogenic switch and metastasis in breast cancer, and therapeutic suppression of WNT7B signaling might be advantageous due to targeting multiple aspects of tumor progression." (PMID 28245581, 2017). "By contrast, in a mouse model of mammary carcinoma, myeloid WNT7b promotes angiogenesis." (PMID 28846685, 2017).
breast carcinoma (continued). "The findings also showed that Wnt7b secreted by ATMs may activate the Wnt signaling pathway in the tumor immune microenvironment through interactions with FZD4, ultimately causing malignant transformation of breast cancer." (PMID 34457116, 2021). "The highest frequency rate of “amplification” of WNT2, WNT7B, and WNT11 was recorded at 3.69%, 15.83%, and 33.25%, respectively, notably within The Metastatic Breast Cancer Project (Provisional, December 2021)." (PMID 41044153, 2025). "E2F1 and E2F4 induce whereas pRb/RBL2 reduce WNT ligand expression (e.g. WNT7A, WNT7B, WNT10A, WNT4) thereby regulating self-renewal, chemoresistance and invasiveness of CSCs in both PDAC and breast cancer, and fibroblast proliferation." (PMID 38678032, 2024). "Eight of these genes (except WNT2, GADD45B, FZD2, WNT7B, POLK, and PIK3R3) have been extensively studied in breast cancer." (PMID 32818022, 2020). "In breast cancer, TAM-secreted wingless-type MMTV integration site family, member 7B (WNT7b) increased VEGF-A expression in vascular endothelial cells to promote angiogenesis." (PMID 32326073, 2020). "For example, previous studies have shown pro-tumorigenic and pro-metastatic role of ERBB2, WNT7b, S100A7, and MMP13 in breast cancer." (PMID 26669540, 2015). "The differential drug sensitivity of WNT2, WNT7B, and WNT11 suggests that these genes may serve as predictive biomarkers for therapeutic responses in breast cancer." (PMID 41044153, 2025). "Proliferation of non-stem breast cancer cells was also affected since depletion of WNT7B/WNT4/WNT3A reduced cell cycle progression while addition of purified WNT7B and WNT4/WNT3A to media had the opposite effect." (PMID 38678032, 2024). "This implies that the interaction of Wnt7b and FZD4 between ATMs (CD68+) and adipocytes (FCs) may contribute to the poor prognosis of breast cancer, mainly in the form of a high BCPRS profile." (PMID 34457116, 2021). "WNT7B is a member of the WNT ligand family and its expression is an important prognostic factor for the overall survival as well as recurrence-free survival of patients with breast cancer." (PMID 34049534, 2021). "As cisplatin increased the canonical Wnt7b in the study, increase of ABCB1 and ABCG2 perhaps is not surprising as previous studies have also demonstrated beta-catenin dependent induction of ABCB1 in breast cancer and ABCG2 in colon cancer." (PMID 28340578, 2017).
prostate carcinoma (13 papers, 2015 to 2025). A carcinoma that arises from epithelial cells of the prostate gland. "Accordingly, a FOXB2/WNT7B gene expression signature was associated with poor prognosis in prostate cancer patient data." (PMID 34298659, 2021). "WNT7B encodes a protein involved in Wnt signaling and has been implicated in several cancer types, including hepatocellular carcinoma, colorectal cancer, and prostate cancer, as well as in metastasis of breast and pancreatic adenocarcinomas." (PMID 41155454, 2025). "WNT7B, WNT9A and WNT10B did indeed cause a small increase in LNCaP cell growth and motility, and WNT7B has been shown to be required for the growth of both androgen-dependent and castration-resistant prostate cancer cells in other studies." (PMID 37373067, 2023). "Inhibition of WNT7B signaling was sufficient to block the effect of FOXB2, and loss-of-function of FOXB2 reduced Wnt transcriptional activity in prostate cancer cell lines." (PMID 34298659, 2021). "Topics enriched in Samples 4 and 16 include genes such as AR, GRHL2, FOXA1, SLC43A1, WNT7B, which are known downstream players active in prostate cancers with ERG expression." (PMID 34911933, 2021). "This supports the hypothesis that WNT7B enhances prostate cancer cell proliferation of by activating PKC-MARCKS signaling." (PMID 36982422, 2023). "In prostate cancer cell lines, knockdown of WNT7B reduced cell proliferation." (PMID 36982422, 2023). "In addition, we explored therapeutic targets by investigating FOXA1 interacting protein within proteins encoded by upregulated genes in FOXA1 mutant prostate cancer, and identified six genes—HSP90AB1, KDM1A, FKBP4, H2BC15, WNT7B, and GRB7." (PMID 37958805, 2023). "Moreover, Wnt7b promotes cancer cell androgen-independent growth by activating protein kinase C isozymes in advanced prostate cancer." (PMID 33912460, 2021). "Wnt7b promotes androgen-independent advanced prostate cancer cell proliferation through a PKC-mediated noncanonical Wnt pathway." (PMID 25999350, 2015). "For instance, overexpression of phb in human prostate cancer cells decreases the expression of several members of WNT family and reduces the motility and invasiveness of cancer cells, and phb plays an important role in the inter-regulation of wnt7b, wnt9a, and wnt10b with the cell cycle." (PMID 37868974, 2023).
glioma (12 papers, 2019 to 2025). A benign or malignant brain and spinal cord tumor that arises from glial cells (astrocytes, oligodendrocytes, ependymal cells). "Expression of Wnt-7b/β-catenin signaling pathway-related proteins was determined to further elucidate the underlying mechanism of OIP5-AS1 in glioma." (PMID 30498093, 2019). "For instance, tumor-associated macrophages participate in all stages of angiogenesis in gliomas by releasing paracrine factors such as WNT7b and M-CSF." (PMID 35579998, 2022). "The novelty of this study was the first report of the molecular mechanism of the circ_0082375/miR-485-5p/Wnt7B axis in glioma." (PMID 34868669, 2021). "Nevertheless, the effects of Wnt7B on glioma cell malignancy, angiogenesis, and glycolysis need to be further studied." (PMID 34868669, 2021). "U-251 and LN-229 cells were cotransfected with miR-485-5p and Wnt7B to alter Wnt7B expression and to peruse whether miR-485-5p exerts a biological role by regulating Wnt7B expression in glioma cells." (PMID 34868669, 2021). "Besides, the authors found that circ_0082375 upregulated Wnt7B expression by sponging miR-485-5p in glioma cells." (PMID 34868669, 2021). "Besides, the impact of the circ_0082375/miR-485-5p/Wnt7B axis on glioma progression was enquired, providing an effective molecular target for glioma therapy." (PMID 34868669, 2021). "Altogether, circ_0082375 regulates Wnt7B expression by sponging miR-485-5p in glioma cells." (PMID 34868669, 2021). "In accordance with previous research, Wnt7B was highly expressed in glioma tissues and cells." (PMID 34868669, 2021). "Furthermore, Wnt7B expression was positively correlated with circ_0082375 expression (P < 0.0001, r = 0.5773) in glioma tissues, whereas it negatively correlated with miR-485-5p expression (P < 0.0001, r = −0.7087)." (PMID 34868669, 2021). "Using the dual-luciferase reporter assay, we also confirmed that Wnt-7b was indeed the target gene of miR-410, suggesting that silencing OIP5-AS1 may affect growth and metastasis of U87 glioma cells via targeted regulation of Wnt-7b by miR-410." (PMID 30498093, 2019). "Notably, the Wnt7b signaling pathway was shown to regulate distinct glioma–vascular interactions and tumor microenvironments." (PMID 30498093, 2019). "Taken together, this research suggested that silencing OIP5-AS1 may specifically block the Wnt-7b/β-catenin pathway via targeted up-regulating miR-410, thereby inhibiting growth, invasion and migration while promoting apoptosis in glioma cells." (PMID 30498093, 2019). "Importantly, Wnt7B regulates cell proliferation and invasion in glioma." (PMID 34868669, 2021). "Moreover, Wnt7B mRNA and protein levels were prominently elevated in 48 cases of glioma tissues." (PMID 34868669, 2021). "Varied expression levels of Wnt pathway components in gliomas have been observed, such as elevated WNT3A and 5A and decreased WNT7B, and the oncogenic role of overexpressed WNT6." (PMID 39874307, 2025). "Therefore, silencing OIP5-AS1 may inhibit the Wnt-7b/β-catenin pathway by up-regulating miR-410, thereby suppressing glioma growth, invasion and migration and promoting apoptosis, deepening understanding of the molecular mechanism of glioma." (PMID 30498093, 2019). "This could be due to residual levels of Wnt signaling within gliomas, as BBB-specific Wnt-ligands (Wnt7a, Wnt7b and Norrin) are expressed by glial lineage cell-types, including oligodendrocyte progenitors and astrocytes." (PMID 34425907, 2021). "Together, our results demonstrated that circ_0082375 increased Wnt7B expression via sponging miR-485-5p to regulate cell proliferation, apoptosis, migration, invasion, angiogenesis, glycolysis, and EMT, thereby affecting glioma progression." (PMID 34868669, 2021). "Western blotting was employed to determine the expression of Wnt-7b/β-catenin pathway-related proteins, while MTT, flow cytometry, Transwell assays and wound-healing assays were used to measure the biological characteristics of glioma cells." (PMID 30498093, 2019).